NUSAP1 (nucleolar and spindle associated protein 1)
Diseases named in the same sentence as NUSAP1 in open-access papers (continued):
Sharing a sentence is not in itself a finding about the gene and the disease.
ovarian carcinoma (3 papers, 2019 to 2022). A malignant neoplasm originating from the surface ovarian epithelium. "High NUSAP1 expression was an independent risk factor affecting the prognosis of patients with epithelial ovarian cancer." (PMID 35739489, 2022). "High NUSAP1 level is an independent risk factor affecting the survival and prognosis of patients with ovarian cancer, especially for patients with early-stage or serous ovarian cancer." (PMID 35739489, 2022). "IHC assay confirmed that NUSAP1 is highly expressed in ovarian cancer and is an independent risk factor for patient survival prognosis." (PMID 35739489, 2022). "Considering BRCA1 is well-known to be associated with ovarian cancer, we assumed that NUSAP1 could also be a promising biomarker for OC." (PMID 31729978, 2019). "Ovarian cancer datasets showed that NUSAP1 expression was significantly upregulated in ovarian cancer." (PMID 35739489, 2022). "Of these studies, 92 showed that the expression of NUSAP1 was significantly upregulated, including three studies in ovarian cancer." (PMID 35739489, 2022). "Database analyses and experimental results demonstrated that NUSAP1 was highly expressed in ovarian cancer, its levels being correlated with the FIGO stage." (PMID 35739489, 2022). "In order to explore the predictive value of NUSAP1 in ovarian cancer immunotherapy response, we analyzed the relationship between NUSAP1 and immune infiltration." (PMID 35739489, 2022). "Our study aimed to explore the clinical significance of NUSAP1 and provide a new research direction for finding biomarkers of ovarian cancer." (PMID 35739489, 2022). "Further analysis of the expression of NUSAP1 in different histological types of ovarian cancer showed that NUSAP1 had the highest positive rate in ovarian clear cell carcinoma." (PMID 35739489, 2022). "In summary, database analyses and IHC assay confirmed that NUSAP1 is highly expressed in ovarian cancer." (PMID 35739489, 2022). "The result of Cox regression analysis, which was consistent with the results of bioinformatics analysis, showed that high NUSAP1 expression conferred poor prognosis of patients with ovarian cancer." (PMID 35739489, 2022). "To investigate the significance of NUSAP1 in epithelial ovarian cancer of different stages, we analyzed the prognostic significance stratified by FIGO stage." (PMID 35739489, 2022). "The potential molecular mechanism of NUSAP1 in ovarian cancer was assessed with respect to homologous recombination repair, mismatch repair, and immunology using different databases." (PMID 35739489, 2022). "NUSAP1 expression was significantly increased in ovarian cancer compared with that of normal tissues, especially in FIGO stage III." (PMID 35739489, 2022). "This study is the first to report the prognostic value of NUSAP1, as well as its involvement in signaling pathways and correlation with immune cell infiltration in ovarian cancer." (PMID 35739489, 2022). "We further compared the tumor infiltration level in ovarian cancer with different somatic copy number variations of NUSAP1." (PMID 35739489, 2022). "We found that NUSAP1 is correlated with DNA repair, replication fork and homologous recombination in ovarian cancer." (PMID 35739489, 2022). "Oncomine, TCGA, CCLE, and UALCAN databases were used to analyze the expression level of NUSAP1 in ovarian cancer." (PMID 35739489, 2022). "We also explored the molecular mechanism of NUSAP1 contributing for the tumorigenesis and progression of ovarian cancer." (PMID 35739489, 2022). "Further investigation using in vitro and in vivo models are needed to validate the biological significance of NUSAP1 in different pathological subtypes of ovarian cancer and to elucidate the molecular mechanism of NUSAP1 in regulating DNA repair." (PMID 35739489, 2022). "Results of IHC assay showed that the positive rate of NUSAP1 in ovarian malignant tumors is significantly higher than that in other groups." (PMID 35739489, 2022).
ovarian carcinoma (continued). "Altogether, NUSAP1 may represent a new biomarker for predicting the efficacy of immunotherapy in ovarian cancer." (PMID 35739489, 2022). "Both Kaplan–Meier survival analysis and Cox regression analysis showed that high expression of NUSAP1 was associated with shorter OS in early-stage, but not in advanced-stage epithelial ovarian cancer." (PMID 35739489, 2022). "Furthermore, the UALCAN database was used to analyze the expression of NUSAP1 in ovarian cancer and its correlation with clinical parameters." (PMID 35739489, 2022). "Moreover, we explored the distribution of NUSAP1 expression across molecular subtypes in ovarian cancer using the TISIDB database." (PMID 35739489, 2022). "Therefore, this study highlights the significant value of NUSAP1 for predicting prognosis and response to chemotherapy and immunotherapy in ovarian cancer." (PMID 35739489, 2022). "NUSAP1 may be a valuable prognostic marker, as well as a novel biomarker for evaluating the response to immunotherapy of patients with ovarian cancer." (PMID 35739489, 2022). "Furthermore, database analyses indicated molecular mechanisms through which NUSAP1 may be involved in ovarian cancer development." (PMID 35739489, 2022). "Therefore, NUSAP1 in ovarian cancer may participate in HRR by regulating the levels of ATR and BRCA1/2; thus, low expression of NUSAP1 in ovarian cancer implies sensitivity to PARP inhibitors." (PMID 35739489, 2022). "Therefore, high NUSAP1 expression may cause increased infiltration of neutrophils and decreased infiltration of CD8 + T cells, leading to the progression and poor prognosis of ovarian cancer." (PMID 35739489, 2022). "A positive correlation was identified between the expression of NUSAP1 and BRCA1/2 in ovarian cancer." (PMID 35739489, 2022). "In addition, both the CCLE and cBioPortal database showed a positive correlation between the expression of NUSAP1 and BRCA1 in ovarian cancer." (PMID 35739489, 2022). "For all patients with ovarian cancer, NUSAP1 could not predict the prognosis of receiving platinum-paclitaxel combination or platinum chemotherapy." (PMID 35739489, 2022). "In addition, the ability of NUSAP1 as a biomarker to predict the efficacy of PARP inhibitors alone or in combination with DNMT inhibitions warrants further evaluation, which will assist in the development of future individualized therapeutic strategies for ovarian cancer." (PMID 35739489, 2022).
cervical squamous cell carcinoma (2 papers, 2019 to 2020). A squamous cell carcinoma arising from the cervical epithelium. "In the present study, we comprehensively investigated the clinicopathological features and potential prognostic value of NUSAP1 in cervical squamous cell carcinoma and endocervical adenocarcinoma (CESC)." (PMID 32226503, 2020).
chronic lymphocytic leukemia (2 papers, 2021 to 2022). "Rad51 expression and stability is critical for nucleolar and spindle-associated protein 1 (NUSAP1)-mediated chemoresistance via DDR signaling in chronic lymphocytic leukemia cells." (PMID 35875146, 2022). "Although NUSAP1 acts as an oncogene involved in the progression of several cancers, the exact role of chronic lymphocytic leukemia (CLL) remains elusive." (PMID 34782617, 2021).
endocervical adenocarcinoma (2 papers, 2019 to 2020). An adenocarcinoma that arises from the endocervix. "Subsequently, the diagnostic and prognostic values of NUSAP1 in carcinoma and endocervical adenocarcinoma (CESC) were determined." (PMID 32226503, 2020).
nasopharyngeal carcinoma (2 papers, 2022 to 2025). A carcinoma arising from the nasopharyngeal epithelium. "It has also been reported that silencing NUSAP1 reduces the Wnt/β-catenin signaling pathway in nasopharyngeal cancer by downregulating phosphorylation of glycogen synthase kinase 3 beta (GSK-3β), reducing cell proliferation, and reducing invasion." (PMID 35710427, 2022). "Research has shown that in nasopharyngeal carcinoma (NPC), the overexpression of NUSAP1 leads to increased phosphorylation of GSK-3B, thereby reducing its enzymatic activity." (PMID 40535133, 2025).
ovarian serous carcinoma (2 papers, 2012 to 2022). "The HPA database evaluated the level of NUSAP1 in ovarian serous carcinoma, mucinous carcinoma, endometrioid carcinoma, and normal tissues using immunohistochemical data." (PMID 35739489, 2022). "Interestingly, hsa-miR-18a, which possesses a significant positive correlation with GINS1 (along with NUSAP1) has shown to be highly up-regulated in serous ovarian carcinoma both previously and within our analysis." (PMID 22452920, 2012).
Parkinson's (2 papers, 2015 to 2024). "These include genes such as NUSAP1 and MS4A6A that are associated to glomerulonephritis, an IgA nephropathy; GPBAR1 that is highly expressed in intestinal monocytes of patients with inflamed Crohn's disease, and; SYNJ1 and PLD3 that are both associated to Parkinson's disease and Alzheimer's disease." (PMID 26338775, 2015). "Parkinson's and Huntington's disease were both enriched by APOC1, NUSAP1, NR4A2, ADRB2 and ZNF331." (PMID 39098992, 2024).
prostate adenocarcinoma (2 papers, 2022 to 2023). "In human prostate adenocarcinoma, NUSAP1 and ILF2 mRNA expression levels are positively correlated, elevated, and associated with poor clinical outcomes." (PMID 37047232, 2023). "In The Cancer Genome Atlas (TCGA) Prostate Adenocarcinoma (PRAD) dataset, NUSAP1 mRNA levels are upregulated in prostate adenocarcinoma tissues compared with non-cancerous prostate tissues." (PMID 37047232, 2023).
adenoma (1 paper, 2013). A neoplasm arising from the epithelium. "Array data mining found that genes such as Ccnb1, Igfbp3, Nusap1, Pttg1, Racgap1, Top2a, Tpx2, which are associated with the aggressive behaviour of various human tumors, including PAs, and proto-oncogenes such as Ect2, Kit, Kras, Lyn, Ret are up-regulated in rat adenomas." (PMID 23756599, 2013).
autoimmune thyroid disease (1 paper, 2022). Inflammatory disease of the thyroid gland due to autoimmune responses leading to lymphocytic infiltration of the gland. "In addition, we used GSEA analysis to determine that NUSAP1 may affect the cell cycle, DNA replication, cell adhesion, the NF-KB signaling pathway, and autoimmune thyroid disease (AITD); high expression of NUSAP1 does indeed participate in the cell cycle pathway." (PMID 35710427, 2022).
cervical adenocarcinoma (1 paper, 2019). An adenocarcinoma arising from the cervical epithelium. "For example, target genes specific to cervical adenocarcinoma cells were most enriched for PANTHER molecular function term DNA binding, bending (e.g., HIST2H2BE, NCAPD3, and NUSAP1)." (PMID 31752429, 2019).
chronic hepatitis (1 paper, 2024). An active inflammatory process affecting the liver for more than six months. "Further investigation is needed to understand the involvement of NUSAP1 in the progression from chronic hepatitis to HCC." (PMID 38441732, 2024).
cleft palate (1 paper, 2024). Cleft palate is a fissure type embryopathy that affects the soft and hard palate to varying degrees. "MEIS2 is linked to cleft palate, cardiac defects, and impaired intellectual development (CPCMR, MIM# 600987), whereas NUSAP1 has been described as tolerant of loss-of-function." (PMID 39639090, 2024).
COVID-19 (1 paper, 2023). A disease caused by infection with severe acute respiratory syndrome coronavirus 2. "In the study of tissue regeneration after acute injury, we analyzed the database of ALF and COVID-19 by bioinformatics method and found common hub genes, including CDC20, CENPF, KIF4, KIF11, NUSAP1, TPX2, and PTTG1, which were related to mitosis and cell cycle regulation." (PMID 36911196, 2023).
developmental delay (1 paper, 2024). "However, a recent publication reported an NUSAP1 nonsense variant in two individuals with microcephaly, severe developmental delay, brain abnormalities, and seizures." (PMID 39639090, 2024).
gonadotroph adenomas (1 paper, 2013). "Two such genes, CYP11A1 and NUSAP1, were analyzed in 39 human gonadotroph adenomas by qRT-PCR and found to be up-regulated in 77 and 95 % of cases, respectively." (PMID 23756599, 2013). "We here report that 90 % of human gonadotroph adenomas express the NUSAP1 gene at high level." (PMID 23756599, 2013).
kidney cancer (1 paper, 2023). Primary or metastatic malignant neoplasm involving the kidney. "High NUSAP1 expression was identified as a risk factor in tumorigenesis and progression, especially in four types of kidney cancer (ACC, KICH, KIRC, and KIRP), as well as LGG, LIHC, LUAD, PAAD, PCPG, PRAD, and SARC." (PMID 37781040, 2023). "Furthermore, NSCLC and kidney cancer patients with high NUSAP1 expression had lower response rates to immunotherapy." (PMID 37781040, 2023). "On the other hand, kidney cancer and LUAD patients with high NUSAP1 are more prone to metastasis and disease progression." (PMID 37781040, 2023). "Survival analysis showed that patients with low NUSAP1 levels exhibited improved PFS in NSCLC) and OS in kidney cancer and SKCM when treated with anti-PD-1/PD-L1 therapy, compared to those with high NUSAP1 levels." (PMID 37781040, 2023).
leukemia (1 paper, 2020). A malignant (clonal) hematologic disorder, involving hematopoietic stem cells and characterized by the presence of primitive or atypical myeloid or lymphoid cells in the bone marrow and the blood. "As revealed by CCLE analysis, the NUSAP1 expression levels in B cell lines and leukemia cell lines were high." (PMID 32226503, 2020).
liver disease (1 paper, 2024). "GSEA analysis was conducted to identify distinctively regulated pathways between the high and low expression groups of NUSAP1, as well as to determine the activated signaling pathways in liver diseases associated with HBV." (PMID 38441732, 2024). "Our findings indicate that elevated NUSAP1 expression is linked to progressive liver diseases, immune cell infiltration and poor prognosis of HCC." (PMID 38441732, 2024). "We downloaded GSE65359, GSE84044 and GSE136247 from the GEO database and analyzed NUSAP1 expression in different status of HBV-related liver diseases." (PMID 38441732, 2024). "This may be due to the role of NUSAP1 in promoting immune evasion of CSCs during the progression of liver disease." (PMID 38441732, 2024).
liver fibrosis (1 paper, 2022). "That may be why NUSAP1 was elevated in NAFLD patients with liver fibrosis, where the capacity of regeneration of the liver by compensatory proliferation is dramatically reduced." (PMID 35431924, 2022).
metastatic disease (1 paper, 2022). "Despite limited effects on cell proliferation, NUSAP1 participates in development of metastatic disease, possibly by regulation of the expression of family with sequence similarity 101 member B (FAM101B)." (PMID 36258196, 2022).
metastatic prostate carcinoma (1 paper, 2017). A carcinoma that arises from the prostate gland and has spread to other anatomic sites. "The finding of increased NUSAP1 expression levels in metastatic prostate cancer argues strongly for its role in progression." (PMID 28404898, 2017).
multiple myeloma (1 paper, 2023). "In multiple myeloma, increased ILF2 is associated with therapeutic resistance mediated through DNA repair pathways, and it is interesting to note that increased expression of NUSAP1 is associated with DNA repair pathways in the PRAD data in our study and others." (PMID 37047232, 2023).
non-alcoholic fatty liver disease (1 paper, 2025). "NUSAP1 has been recognized as a specific gene involved in the progression from non-alcoholic fatty liver disease (NAFLD), HBV infection, and liver cirrhosis to HCC." (PMID 40535133, 2025).
oral carcinoma (1 paper, 2015). "Thus, we investigated the expression profiles and biological functions of NUSAP1 to clarify the roles of NUSAP1 in oral carcinoma." (PMID 26554377, 2015). "Our previous DNA microarray analysis revealed the up-regulated expression of NUSAP1 in oral carcinoma, suggesting that NUSAP1 may be related to oral carcinoma." (PMID 26554377, 2015).
ovarian clear cell cancer (1 paper, 2022). An invasive malignant neoplasm that arises from the ovary and is characterized by a predominance of clear and hobnail malignant epithelial cells. "NUSAP1 showed the highest positive rate in ovarian clear cell carcinoma." (PMID 35739489, 2022).
ovarian endometrioid cancer (1 paper, 2022). "Upregulation of NUSAP1 was correlated with poor OS in ovarian serous cancer, but not in ovarian endometrioid cancer." (PMID 35739489, 2022).
ovarian epithelial malignant tumors (1 paper, 2022). "Seventy-eight patients with ovarian epithelial malignant tumors were divided into two groups according to the NUSAP1 expression level." (PMID 35739489, 2022).
papillary thyroid carcinoma (1 paper, 2025). "Both LINC02913 and miRNA hsa-miR-545-3p were involved in a competing endogenous RNA network of mRNA nucleolar spindle-associated protein 1 (NUSAP1) in papillary thyroid carcinoma." (PMID 41387767, 2025).
sarcopenia (1 paper, 2025). Progressive decline in muscle mass due to aging which results in decreased functional capacity of muscles. "MMP24‐AS1, HLA‐DRB6, HLA‐DQA2, DDX42, BAG6, NUSAP1, LINC00940, NME1‐NME2 and AS3MT in the amygdala region showed detrimental effect on all the five sarcopenia‐related traits, whereas HLA‐DRB1, HLA‐DQB1‐AS1 and C6ORF3 showed protective effect (p < 0.05)." (PMID 39535371, 2025). "The over‐expression of nine genes (MMP24‐AS1, HLA‐DRB6, HLA‐DQA2, DDX42, BAG6, NUSAP1, LINC00940, NME1‐NME2 and AS3MT) in the amygdala region showing detrimental effect on all the five sarcopenia‐related traits, whereas three genes (HLA‐DRB1, HLA‐DQB1‐AS1 and C6ORF3) showing protective effect." (PMID 39535371, 2025).
serous ovarian cancer (1 paper, 2022). "Kaplan–Meier survival analysis showed that for patients with serous and non-serous ovarian cancer, high expression of NUSAP1 was associated with poor OS." (PMID 35739489, 2022). "Further analysis showed that high NUSAP1 expression conferred poor OS in high-grade serous ovarian cancer (HGSC), especially in the early-stage." (PMID 35739489, 2022). "The results of bioinformatics analysis and immunohistochemistry statistics indicated that high expression of NUSAP1 was correlated with poor OS of patients with serous ovarian cancer." (PMID 35739489, 2022). "By univariate analysis, NUSAP1 expression and residual tumor size predicted poor OS in serous ovarian cancer." (PMID 35739489, 2022). "Surprisingly, serous ovarian cancer patients with high NUSAP1 expression had a poor prognosis after receiving these chemotherapy regimens." (PMID 35739489, 2022). "In addition, the high-positive rate of NUSAP1 in HGSC was higher than that in low-grade serous ovarian cancer." (PMID 35739489, 2022). "Therefore, NUSAP1 upregulation may be related to platinum and docetaxel-based chemotherapy resistance in patients with serous ovarian cancer." (PMID 35739489, 2022).
tauopathy (1 paper, 2023). Neurodegenerative disorders involving deposition of abnormal tau protein isoforms (tau proteins) in neurons and glial cells in the brain. "Our study is the first to report that a loss of function of NUSAP1 can facilitate tau aggregation and that the protein is down-regulated in AD brain samples, potentially leading to nucleolar dysfunction and thereby enhancing tauopathy." (PMID 36316035, 2023). "Intriguingly, at least three gene products, VPS18, NUSAP1, and EIF1AD, were found to be down-regulated in the AD brain, supporting their potential relevance in the emergence or propagation of tauopathy." (PMID 36316035, 2023). "Furthermore, we showed that VPS18, NUSAP1, and EIF1AD are all down-regulated in AD brain samples, supporting the notion that these regulators may be important for the development of tauopathy in the human brain." (PMID 36316035, 2023).
thyroid cancer (1 paper, 2022). "Therefore, it is conjectured that NUSAP1 also performs certain biological functions in thyroid cancer." (PMID 35710427, 2022).